FAS (Fas cell surface death receptor)
Description:
Receptor for TNFSF6/FASLG. The adapter molecule FADD recruits caspase CASP8 to the activated receptor. The resulting death-inducing signaling complex (DISC) performs CASP8 proteolytic activation which initiates the subsequent cascade of caspases (aspartate-specific cysteine proteases) mediating apoptosis. FAS-mediated apoptosis may have a role in the induction of peripheral tolerance, in the antigen-stimulated suicide of mature T-cells, or both. The secreted isoforms 2 to 6 block apoptosis (in vitro).
Synonyms: CD95; APT1; FAS1; TNFRSF6; APO-1; ALPS1A; FASTM
Tractability: Antibody: UniProt places it where antibodies can reach, with high confidence; its Gene Ontology location is reachable by antibodies, with high confidence; UniProt predicts a signal peptide or a membrane-spanning region; the Human Protein Atlas places it where antibodies can reach. PROTAC: ubiquitination databases record sites on it; its protein half-life has been measured.
Target class: Membrane receptor
Chemical probes: BI 99179 (high quality)
Gene: Protein-coding gene on chromosome 10 (88,953,813 to 89,029,605, forward strand). Ensembl gene ENSG00000026103.
Subcellular location: Cell membrane (Isoform 1); Membrane raft; Secreted (Isoform 2); Secreted (Isoform 3); Secreted (Isoform 4); Secreted (Isoform 5); Secreted (Isoform 6)
Subcellular location (Human Protein Atlas): Plasma membrane; Cytosol; Nuclear bodies; Predicted to be secreted
Pathways (Reactome):
Programmed Cell Death: CASP8 activity is inhibited; Caspase activation via Death Receptors in the presence of ligand; Dimerization of procaspase-8; RIPK1-mediated regulated necrosis; Regulation by c-FLIP
Signal Transduction: FasL/ CD95L signaling
Gene Ontology:
Molecular function: calmodulin binding; identical protein binding; kinase binding; protein binding; tumor necrosis factor receptor activity; signaling receptor activity; transmembrane signaling receptor activity
Biological process: apoptotic process; cellular response to amino acid starvation; cellular response to hyperoxia; cellular response to mechanical stimulus; extrinsic apoptotic signaling pathway; extrinsic apoptotic signaling pathway via death domain receptors; Fas signaling pathway; necroptotic signaling pathway; positive regulation of apoptotic process; positive regulation of apoptotic signaling pathway; positive regulation of reactive oxygen species biosynthetic process; regulation of stress-activated MAPK cascade; activation-induced cell death of T cells; motor neuron apoptotic process; negative regulation of apoptotic process; protein-containing complex assembly; regulation of apoptotic process; signal transduction; immune response; tumor necrosis factor-mediated signaling pathway
Cellular component: CD95 death-inducing signaling complex; cell surface; death-inducing signaling complex; extracellular exosome; membrane raft; plasma membrane; cytosol; external side of plasma membrane; extracellular region; membrane
Genetic constraint (gnomAD): Loss-of-function variants: 6 observed, 31.86 expected, observed/expected ratio (o/e) 0.19, 90% interval 0.1 to 0.37. The upper end of that interval is the gene's LOEUF score, 0.37, which puts it in group 1 of 6, group 1 being the genes least tolerant of losing a copy. Missense variants: 325 observed, 393.2 expected, observed/expected ratio (o/e) 0.83, 90% interval 0.75 to 0.91. Synonymous variants: 128 observed, 134.87 expected, observed/expected ratio (o/e) 0.95, 90% interval 0.82 to 1.1.
Cancer hallmarks: cell replicative immortality (promotes); escaping programmed cell death (promotes); escaping programmed cell death (suppresses); invasion and metastasis (promotes); proliferative signalling (promotes)
Homologues: Orthologues: chimpanzee FAS (91% identical), pig FAS (57% identical), rabbit FAS (57% identical), guinea pig FAS (53% identical), dog FAS (49% identical), mouse Fas (49% identical), rat Fas (49% identical), tropical clawed frog fas (28% identical). Paralogues in human: TNFRSF1A (17% identical), LTBR (16% identical), TNFRSF25 (16% identical), TNFRSF11A (16% identical), TNFRSF10B (15% identical), TNFRSF21 (15% identical), NGFR (14% identical), TNFRSF10A (14% identical), TNFRSF1B (14% identical), CD40 (14% identical), RELT (13% identical), TNFRSF11B (13% identical), and 9 more.
Diseases named in the same sentence as FAS in open-access papers:
FAS is named in the same sentence as 369 diseases in open-access papers, as found by Europe PMC text mining. Sharing a sentence is not in itself a finding about the gene and the disease. The quoted sentences say what the papers report.
autoimmune lymphoproliferative syndrome (115 papers, 2007 to 2026). Autoimmune lymphoproliferative syndrome (ALPS) is a rare, inherited disorder characterized by non-malignant lymphoproliferation, multilineage cytopenias, and a lifelong increased risk of Hodgkin's and non-Hodgkin's lymphoma. "Autoimmune lymphoproliferative syndrome with FAS mutations (ALPS-FAS) is also associated with hyperactivation of the mTOR pathway but hematologic symptoms are more severe than ALPS-CED." (PMID 41026346, 2025). "For instance, loss‐of‐function mutations in FAS (as in autoimmune lymphoproliferative syndrome) fail to delete autoreactive lymphocytes and cause systemic autoimmunity." (PMID 41294018, 2025). "In autoimmune lymphoproliferative syndrome (ALPS) patients carrying mutations in FAS (ALPS‐FAS), we detected increased PI3K/AKT/mTOR activity in tissue‐resident B cells and an enhanced EF response, concomitant with strongly reduced GCs." (PMID 39917832, 2025). "For example, somatic variants in the FAS-pathway cause autoimmune lymphoproliferative syndrome (ALPS)." (PMID 38659694, 2024). "Its first clinical description dates back to the 1960s, when it was formerly known as Canale-Smith syndrome, while the first disease-causing mutations were reported in 1995 as a germline mono-allelic mutation of FAS." (PMID 38704374, 2024). "For example, a somatic, heterozygous pathogenic variant of FAS is a known cause of autoimmune lymphoproliferative syndrome." (PMID 37325673, 2023). "In fact, impairment of FAS-mediated apoptosis by mutations in FAS gene causes autoimmune lymphoproliferative syndrome characterized by chronic lymphoproliferation and autoimmune manifestations." (PMID 35013338, 2022). "Autoimmune lymphoproliferative syndrome (ALPS) is mainly caused by mutations in FAS mediated apoptosis pathway." (PMID 33489922, 2020). "Downregulation of FAS in GCs by miR-146a was also reported to cause autoimmune lymphoproliferative syndrome in mice, which is indicative of a critical role of miR-146a in B-cell homeostasis and GC response through FAS." (PMID 32210951, 2020). "Except for the patient with autoimmune lymphoproliferative syndrome (ALPS) due to FAS mutation, all had decreased absolute counts of CD3+ T-cells compared to controls." (PMID 32265901, 2020). "For instance, inactivation of the apoptotic mediators FAS/FASL causes autoimmune lymphoproliferative syndrome (ALPS) in humans and is also the basis of some murine lupus models." (PMID 29568300, 2018). "We did also report a novel form of autoimmune lymphoproliferative syndrome caused by homozygous FAS mutations with normal or residual protein expression as well as a novel AR transcription factor 3 deficiency." (PMID 28702026, 2017). "MIR107 plays a role in inhibiting differentiation in granulocytic, monocytic, and B-lymphoid lines, whereas FAS is involved with apoptosis, and mutations in FAS are known to cause autoimmune lymphoproliferative syndrome." (PMID 22087757, 2011). "Similarly, mutations in FAS cause autoimmune lymphoproliferative syndrome (ALPS), an IEI and disease of immune dysregulation." (PMID 39241920, 2024). "Casp8−/−Ripk3−/− and Casp8−/−Mlkl−/− mice, characterized by splenomegaly with a marked accumulation of CD3+CD4−CD8−B220+ T cells, resemble the deficiency of FAS ligand (FasL, CD95L) or FAS (CD95) in mice or the autoimmune lymphoproliferative syndrome (ALPS) in humans." (PMID 35064213, 2022). "Indeed, a mutation in FAS causes autoimmune lymphoproliferative syndrome, a different clinical disease from SLE." (PMID 31888754, 2019). "Besides NMZL, FAS is frequently mutated in in patients suffering from the autoimmune lymphoproliferative syndrome, in adult T-cell lymphoma, and diffuse large B-cell lymphoma." (PMID 29556019, 2018). "Lymphoproliferation in autoimmune lymphoproliferative syndrome (ALPS) due to FAS deficiency is driven by highly proliferative FAS-controlled T cells (FCT) with a distinct molecular signature." (PMID 42136947, 2026).
autoimmune lymphoproliferative syndrome (continued). "Additionally, heterozygous germline mutations in the FAS gene associated with autoimmune lymphoproliferative syndrome (ALPS) type I may be linked to RDD." (PMID 40282877, 2025). "Gu and co-authors published the case describing a patient with a de novo variant in the FAS gene presenting a severe phenotype of ALPS (Autoimmune Lymphoproliferative Syndrome)." (PMID 39975544, 2025). "Autoimmune lymphoproliferative syndrome (ALPS) is an inherited lymphoproliferative disorder caused by mutations in the genes encoding for FAS pathway proteins and receptors." (PMID 40993354, 2025). "Autoimmune lymphoproliferative syndrome (ALPS) initially appeared to fit this mold, in that penetrance seemed to be a function of the location of the FAS variant, the most common cause of ALPS." (PMID 41608500, 2025). "Autoimmune lymphoproliferative syndrome (ALPS) is due to autosomal dominant and somatic defects in the genes encoding FAS or FADD, leading to accumulation of activated T cells that have presumably escaped peripheral tolerance mechanisms." (PMID 40842819, 2025). "Eleven patients (25%) with autoimmune lymphoproliferative syndrome (ALPS) due to germline and somatic FAS gene variants along with a germline FASL gene variant were the most common pathogenic finding." (PMID 38363452, 2024). "Some CHIP mutations affect both the T and B-cell compartments, as in the case of FAS deficiency leading to autoimmune lymphoproliferative syndrome (ALPS)." (PMID 36599826, 2023). "Defects in FAS cause autoimmune lymphoproliferative syndrome (ALPS), which is characterized by autoimmunity, particularly against components of the blood; lymphoproliferation including lymphadenopathy; and an increased risk for lymphoma." (PMID 37780853, 2023). "On the other hand, the FAS gene, underlying autoimmune lymphoproliferative syndrome (ALPS), is an interesting example of various genetic mechanisms converging in similar phenotypes." (PMID 36289407, 2023). "Conversely, the CD4−CD8− double-negative (DN) αβ T lymphocyte population was expanded (∼5% of circulating leukocytes), similar to the FAS-deficient patient simultaneously studied who manifested as an autoimmune lymphoproliferative syndrome (ALPS)." (PMID 36326697, 2023). "Prenatal manifestations were observed in a few fetuses with a genomic homozygous deletion of FAS-encoding-gene, the most frequent underlying defect in Autoimmune Lymphoproliferative Syndrome (ALPS)." (PMID 35601409, 2022). "We identified a T158fs FAS mutation in P14, presenting with both a family history and clinical signs of autoimmune lymphoproliferative syndrome (ALPS), including high DNT frequency (21.75%) and AIHA." (PMID 35058929, 2021). "Other diseases identified within this category included two cases of autoimmune lymphoproliferative syndrome (ALPS), both based on pathogenic FAS variants." (PMID 34992599, 2021). "The autoimmune lymphoproliferative syndrome (ALPS) in its most common variant, is caused by germline loss of function mutations in the FAS gene." (PMID 31191551, 2019). "Autoimmune lymphoproliferative syndrome (ALPS) is a rare autoimmune disease mainly caused by mutations in FAS-mediated apoptotic pathway genes." (PMID 30459768, 2018). "MRLlpr/lpr mice were found to carry a loss-of-function mutation of the FAS gene, which was followed by identification of the corresponding human disease, which was named autoimmune lymphoproliferative syndrome (ALPS)." (PMID 28097158, 2016). "Autoimmune lymphoproliferative syndrome (ALPS) is a Mendelian disorder of lymphocyte homeostasis caused by defects in FAS-mediated apoptosis." (PMID 25374737, 2013).
autoimmune lymphoproliferative syndrome (continued). "Autoimmune lymphoproliferative syndrome (ALPS), caused by mutations in the FAS gene, highlights the importance of activation-induced cell death (AICD) in regulating lymphocyte homeostasis." (PMID 40852720, 2025). "Autoimmune Lymphoproliferative Syndrome (ALPS) is a rare immunological disorder caused by defective apoptosis, commonly due to pathogenic variants in the FAS gene." (PMID 40755914, 2025). "The primary cause of autoimmune lymphoproliferative syndrome (ALPS), a condition marked by immunological dysregulation brought on by disturbed lymphocyte homeostasis, is mutations in the FAS-mediated apoptotic pathway." (PMID 37809154, 2023). "The discovery of humans with a similar lymphoproliferative phenotype and harboring heterozygous loss-of-function FAS mutations, dubbed Autoimmune Lymphoproliferative Syndrome (ALPS), further solidified FAS-induced apoptosis as a critical player in maintaining lymphocyte homeostasis." (PMID 38074985, 2023). "Autoimmune lymphoproliferative syndrome (ALPS) and ALP-like syndromes are defects of lymphocyte homeostasis caused by impairment of the FAS-mediated apoptosis pathway." (PMID 38022498, 2023). "Autoimmune lymphoproliferative syndrome (ALPS) is a group of disorders primarily due to impaired lymphocyte apoptosis, whose typical forms are caused by defects in the FAS pathway (FAS, FASLG, and CASP10)." (PMID 35601409, 2022). "Interestingly, PA-IgM and PA-IgG were present in a patient with autoimmune lymphoproliferative syndrome (ALPS) (due to homozygous mutation in FAS) and normal platelet count (188000 per uL)." (PMID 33868317, 2021). "Furthermore, patients with autoimmune lymphoproliferative syndrome (ALPS) have been shown to carry somatic or germline mutations in the genes that encode FAS, Fas-ligand, caspase 10, caspase 8, NRAS, and KRAS." (PMID 32121251, 2020). "Defective FAS-FASL apoptotic pathway leads to a lymphoproliferative syndrome with autoimmune features (autoimmune lymphoproliferative syndrome; ALPS; OMIM 601859)." (PMID 32151092, 2020). "Autoimmune lymphoproliferative syndrome (ALPS) is caused by germline or somatic loss of function FAS mutations resulting in impaired apoptosis and consequent expansion of T-lymphocytes causing organomegaly and autoimmune anemia, neutropenia and thrombocytopenia." (PMID 31191551, 2019). "Indeed, in autoimmune lymphoproliferative syndrome (ALPS), heterozygous germline mutations in the FAS gene inherited in an AD mode and associated with preserved protein expression are the most common cause of ALPS." (PMID 28702026, 2017). "Autoimmune lymphoproliferative syndrome–FAS was identified in three children upon initial diagnosis of ES (two simultaneous, one sequential)." (PMID 26484337, 2015). "Autoimmune lymphoproliferative syndrome (ALPS), characterized by chronic lymphoproliferation, autoimmune manifestations, and an increased lymphoma risk, stems from defects in lymphocyte apoptosis, particularly in components of the apoptotic pathway (e.g., FAS, FASL, FADD, CASP10, and CASP8)." (PMID 38535602, 2024). "Other IEIs with somatic mosaicism as a reported etiology include but are not limited to FAS-related autoimmune lymphoproliferative syndrome; TLR8-related immunodeficiency with bone marrow failure; and UBA1-related severe and often fatal, adult-onset autoinflammatory disease." (PMID 37780853, 2023). "Tests showed increased “double negative” TCRαβ+CD4-CD8- T (DNT) cells and a pathogenic FAS variant, which confirmed a diagnosis of autoimmune lymphoproliferative syndrome (ALPS)." (PMID 35924244, 2022). "Autoimmune lymphoproliferative syndrome (ALPS) is a primary immune regulatory disorder clinically defined by chronic and benign lymphoproliferation, autoimmunity and an increased risk of lymphoma due to a genetic defect in the FAS-FASL apoptotic pathway." (PMID 33995372, 2021).
autoimmune lymphoproliferative syndrome (continued). "The first identified non-malignant autoimmune disease caused by a somatic mutation was in children with symptoms resembling lymphoproliferative syndrome (ALPS, also known as Canale-Smith syndrome) but lacked the inherited germinal mutation in the FAS gene." (PMID 34440825, 2021). "FAS mutations are rarely homozygous and are not exclusively restricted to cancer with several mutations reported in the autoimmune disease autoimmune lymphoproliferative syndrome (ALPS)." (PMID 27843441, 2016). "For example, in autoimmune lymphoproliferative syndrome type IA (ALPS-FAS), defective FAS signaling has been shown to impair mTOR activation and B cell differentiation without inducing apoptosis." (PMID 39843653, 2025). "The Mendelian disease autoimmune lymphoproliferative syndrome (ALPS) arises from defects in the genes FAS, CASP8, and CASP10, which coordinate the Fas-dependent apoptosis that is critical for thymocyte development." (PMID 38589365, 2024). "It was initially reported in a patient presenting autoimmune lymphoproliferative syndrome (ALPS)-like symptom with normal FAS-mediated apoptotic pathway." (PMID 35361277, 2022). "Mendelian syndromes such as autoimmune lymphoproliferative syndrome (ALPS) and TNF receptor associated periodic syndrome (TRAPS) are caused by mutations in FAS (or other members of the FAS signalling pathway) and TNFRSF1A, respectively." (PMID 27435189, 2016). "GD may exhibit autoimmune lymphoproliferative syndrome (ALPS)-like characteristics and defects in FAS-mediated apoptosis." (PMID 40980139, 2025). "Autoimmune lymphoproliferative syndrome (ALPS) and ALPS-like syndromes are conditions characterized by defects in the FAS-mediated apoptosis pathway, leading to an imbalance of lymphocytes and autoimmune manifestations." (PMID 39062908, 2024). "This variant could contribute to a protective role against the haploinsufficient forms of autoimmune lymphoproliferative syndrome (ALPS, OMIM 601859) by increasing the expression of FAS in heterozygous loss-of-function variant carriers." (PMID 35264221, 2022). "miR-146a, which targets Fas, was shown to be involved in the pathogenesis of autoimmune lymphoproliferative syndrome (ALPS), whereas the miR-196b-induced reduction in FAS expression significantly promoted leukemogenesis." (PMID 32182776, 2020). "Autoimmune lymphoproliferative syndrome (ALPS) with FAS mutation (ALPS-FAS) is a nonmalignant, noninfectious, lymphoproliferative disease with autoimmunity." (PMID 29686686, 2018). "Disturbed apoptosis may be involved in SLE and other autoimmune/inflammatory conditions, and mutations in the FAS (Fas cell surface death receptor) or FASL (Fas ligand) genes, regulators of activation-induced cell death, result in autoimmune lymphoproliferative syndrome (ALPS)." (PMID 33569643, 2021). "Autoimmune lymphoproliferative syndrome (ALPS) is characterized by nonmalignant organomegaly, immune cytopenia, and an increased risk for lymphoma, as well as mutation in the FAS-mediated apoptotic pathway." (PMID 33375216, 2021). "Autoimmune lymphoproliferative syndrome (ALPS) is a disorder where immune cells do not undergo apoptosis and proliferation because of a defect in a molecule in the FAS/FASL signal pathway." (PMID 33766139, 2021).